DIPK1C (divergent protein kinase domain 1C)
Synonyms: C18orf51; FAM69C; FNCAD
Tractability: Antibody: UniProt predicts a signal peptide or a membrane-spanning region. PROTAC: ubiquitination databases record sites on it.
Gene: Protein-coding gene on chromosome 18 (74,434,775 to 74,457,944, reverse strand). Ensembl gene ENSG00000187773.
Subcellular location: Endoplasmic reticulum membrane
Gene Ontology:
Molecular function: protein serine/threonine kinase activity
Cellular component: endoplasmic reticulum membrane
Genetic constraint (gnomAD): Loss-of-function variants: 36 observed, 24.18 expected, observed/expected ratio (o/e) 1.49, 90% interval 1.14 to 1.88. The upper end of that interval is the gene's LOEUF score, 1.88, which puts it in group 6 of 6, group 1 being the genes least tolerant of losing a copy. Missense variants: 563 observed, 500.21 expected, observed/expected ratio (o/e) 1.13, 90% interval 1.05 to 1.21. Synonymous variants: 251 observed, 216.82 expected, observed/expected ratio (o/e) 1.16, 90% interval 1.04 to 1.28.
Homologues: Orthologues: chimpanzee DIPK1C (98% identical), macaque DIPK1C (96% identical), mouse Dipk1c (80% identical), rat Dipk1c (79% identical), dog DIPK1C (78% identical), pig DIPK1C (75% identical), rabbit DIPK1C (68% identical), tropical clawed frog dipk1c (50% identical), zebrafish dipk1c (49% identical), Caenorhabditis elegans C53D5.1 (21% identical), Drosophila melanogaster aln (19% identical). Paralogues in human: DIPK1B (23% identical), DIPK1A (21% identical).
Diseases named in the same sentence as DIPK1C in open-access papers:
DIPK1C is named in the same sentence as 2 diseases in open-access papers, as found by Europe PMC text mining. Sharing a sentence is not in itself a finding about the gene and the disease.
DIPK1C shares sentences with these, for which no sentence is quoted: neurodegenerative disease (1 paper); neurological disorders (1).